SNORA74C-2 (small nucleolar RNA, H/ACA box 74C-2)
Gene: Small nucleolar RNA gene on chromosome 10 (49,954,214 to 49,954,414, forward strand). Ensembl gene ENSG00000288603.
Gene Ontology:
Biological process: RNA processing
Cellular component: nucleolus
Homologues: Orthologues: chimpanzee SNORA74 (99% identical), macaque SNORA74 (95% identical), dog SNORA74 (89% identical), pig SNORA74 (85% identical), rabbit SNORA74 (85% identical), mouse Gm23946 (77% identical), guinea pig SNORA74 (75% identical), rat LOC120097670 (72% identical), tropical clawed frog SNORA74 (62% identical), tropical clawed frog SNORA74 (61% identical), tropical clawed frog SNORA74 (50% identical). Paralogues in human: SNORA74C-1 (98% identical), SNORA74B (90% identical), SNORA74 (71% identical), SNORA74A (59% identical), SNORA74 (56% identical), SNORA74D (35% identical), SNORA74 (34% identical).